RHOA (ras homolog family member A)
Diseases named in the same sentence as RHOA in open-access papers (continued):
Sharing a sentence is not in itself a finding about the gene and the disease.
colitis (11 papers, 2017 to 2024). Inflammation of the colon. "Loss of Pggt1b in the T cells of mice also causes spontaneous colitis via impaired RhoA signaling, and the intestinal T cells of IBD patients have lower Pggt1b level." (PMID 36690621, 2023). "In colitis models, inhibition of RhoA/ROCK activity significantly protects the intestinal epithelial barrier dysfunction and colonic inflammation via STAT3 and NF-κB signaling pathways." (PMID 36286060, 2022). "In conclusion, these findings indicate that CSE-derived H2S can preserve the function of EGCs via inhibiting the reactive proliferation and promote EGCs transformation, and inhibition of the RhoA/ROCK signal pathway in mice model of colitis induced by DSS." (PMID 36189321, 2022). "RhoA/ROCK pathway was significantly upregulated in colon of colitis mice, which was more evident in KO mice." (PMID 36189321, 2022). "The role of CSE-produced H2S on EGCs and the RhoA/ROCK signaling pathway was investigated in experimental colitis using CSE knockout (KO) and wild-type (WT) mice." (PMID 36189321, 2022). "In the present study, our findings indicate that CSE-derived H2S can promote the recovery of mice gut functional deficits from DSS-induced colitis via inhibition of the RhoA/ROCK signal pathway." (PMID 36189321, 2022). "Collectively, these reports suggested that RhoA/ROCK activity plays an important role in the pathogenesis of colitis and colonic inflammation." (PMID 36286060, 2022). "SSP significantly improved the clinical symptoms of colitis in rats and reduced the expression of p-RhoA, ROCK1, PI3K, and Akt in the colon mucosa, while it increased the expression of p-Rac and related proteins (Claudin-5, JAM1, VE-cadherin, and Connexin 43)." (PMID 34925530, 2021). "In humans, increased expression of leptin receptor OBR in the mucosa of UC patients is associated with RHOA activation, while deficiency of OBR in mice protects against TNBS colitis in mice." (PMID 33406731, 2021). "The link between RhoA and intestinal inflammation was first shown in 2003, when increased RhoA activation in experimental colitis and patients suffering from IBD was identified." (PMID 29051760, 2017). "However, continuous treatment with NaHS from day one after colitis decreased the expression of RhoA, ROCK1, and ROCK2 proteins in CSE KO and WT mice." (PMID 36189321, 2022). "However, the effect and mechanism of endogenous H2S on the EGCs function and RhoA/ROCK signaling pathway following colitis are still unclear." (PMID 36189321, 2022). "These therapeutic effects were mediated by inhibiting the NF-κB-STAT3 signaling pathway and RhoA/Rho-associated kinase (ROCK) activity, which controls colonic inflammation, F-actin polymerization, and plays an important role in the pathogenesis of colitis." (PMID 36286060, 2022). "Blocking RhoA/Rho-kinase pathway prevents experimental colitis via NF-κB inhibition." (PMID 35740272, 2022). "Our findings show that RhoA/ROCK signal pathway is upregulated in colitis mice." (PMID 36189321, 2022). "Prenylation of RhoA has been shown to control T helper 17 (Th17) cell-mediated colitis." (PMID 34721389, 2021). "Paradoxically, miR-31-3p protects against TNBS and DSS-induced colitis upon activation of RHOA." (PMID 33406731, 2021). "Consequently, these findings suggest that BA treatment may play an important role in DSS-induced colitis by regulating RhoA/ROCK activity." (PMID 36286060, 2022). "RhoA dysfunction in T cells promoted IL-1β, IL-17A, TNF-α, and IFN-γ expression in mice developing spontaneous colitis and blocking RhoA activation reduced IL-2 production." (PMID 36690621, 2023). "MiR-31-3p alleviates colitis in IBD mouse models, possibly by targeting and negatively regulating RhoA expression, thus reducing the levels of several cytokines in colonic epithelial cells." (PMID 36690621, 2023).
colitis (continued). "In IBD patients, T cells isolated from gut tissues showed decreased expression of Pggt1b, which led to dysfunction of RhoA in IECs and T cells in mice, promoting CD4 + T cell accumulating at the intestine and aggravating colitis." (PMID 36690621, 2023). "It is known that STAT3-NF-κB and RhoA/ROCK signaling pathway is closely correlated with epithelial barrier dysfunction and conical inflammation in the colitis model." (PMID 36286060, 2022). "The expression of RhoA, ROCK1 and ROCK2 was significantly increased in colitis." (PMID 36189321, 2022). "Therefore, it is not surprising that colitis-induced RhoA, ROCK1, and ROCK2 expression levels were even higher in CSE KO mice than in WT mice." (PMID 36189321, 2022).
endometrial cancer (11 papers, 2016 to 2025). Primary or metastatic malignant neoplasm involving the endometrium (mucous membrane that lines the endometrial cavity). "In endometrial cancer cells, the expression of RhoA and its downstream effector molecule ROCK was caused by a high concentration of free calcium ions, and its expression level increased with the increase of calcium ion concentration." (PMID 40655948, 2025). "The RBD pull-down results showed that overexpression of wild-type p190A in 293T cells decreased the amount of active RhoA compared with that in control cells and all endometrial cancer-associated p190A mutants, except p190A-S866F, showed impaired RhoGAP activities." (PMID 32457342, 2020). "It should be noted that inactivation of ARHGAP35 leads to abnormal activation of RhoA in endometrial cancer and promotes the malignant transformation of tumor cells through the Hippo-Yap pathway, consistent with the conclusions reported in this study." (PMID 36691027, 2023). "Furthermore, TRPV4 regulates the cytoskeleton of endometrial cancer cells through the RhoA/ROCK1 pathway, thereby promoting metastasis." (PMID 39895789, 2025). "Calcium also activates RhoA in disease states, including brain, colon, and endometrial cancer." (PMID 39517770, 2024). "We first confirmed that p190A was an inhibitor of RhoA-GTP in endometrial cancer cells: p190A depletion increased the active RhoA level, as assessed by the Rho binding domain (RBD) pull-down assay, and the intensity of phospho-MLC (surrogate marker for RhoA activity), as indicated by IF analysis." (PMID 32457342, 2020). "In addition, although the possibility that change in Rho GTPase activity in EC occurs due to mutation changes cannot be completely ruled out, no case of any RhoA GTpase mutation in endometrial cancer has been reported to date." (PMID 32443784, 2020). "And through the correlation analysis of the expressions of ECT2 and RhoA, ROCK1, and ROCK2 in endometrial cancer samples in TCGA database, it was found that the expression of ECT2 was significantly positively correlated with RHOA, ROCK1, and ROCK2." (PMID 40655948, 2025). "Aberrant RhoA activation can, in turn, induce YAP activation leading to proliferation, metastasis, and epithelial-mesenchymal transition in endometrial cancer cells." (PMID 34627383, 2021). "Therefore, different p190A mutations may have divergent effects on p190A activities, and not all p190A mutations can lead to activation of the RhoA-YAP axis in endometrial cancer." (PMID 32457342, 2020). "Moreover, RhoA/ROCK1/LIMK/Cofilin signaling pathway has been reported to induce motility-related changes in the actin cytoskeleton and cell migration of endometrial cancer." (PMID 35379791, 2022).
Sepsis (11 papers, 2015 to 2026). Sepsis is defined as life-threatening organ dysfunction caused by a dysregulated host response to infection. "Highlighting the importance of RhoA signaling, the complement product, C5a (an anaphylatoxin implicated in sepsis pathogenesis), inhibits RhoA activation in a PI3Kδ‐dependent manner, which prevents actin polymerization and reduces neutrophil phagocytosis." (PMID 36440666, 2023). "Several studies in rodent sepsis models showed involvement of Rac1 and/or RhoA GTPases in the development of sepsis-associated microvascular leakage and inflammation." (PMID 35634305, 2022). "The findings described in this review indicate that Rho proteins, mainly RhoA and Rac1, are associated with the development of crucial sepsis-associated dysfunction in different systems and cells, including the endothelium, vessels, and heart." (PMID 34440613, 2021). "The impaired activity of Rho-associated pathways, mainly increased activity of RhoA and the inhibition of Rac1, are listed in several studies associated with experimental sepsis models." (PMID 34440613, 2021). "The relevance of RhoA-mediated signaling transduction for the activity of platelets in sepsis has been suggested in studies involving both animals and human subjects." (PMID 34440613, 2021). "In this way, the use of microRNA in sepsis and endotoxemia can reduce pulmonary inflammation by inhibiting RhoA/ROCK activation." (PMID 34440613, 2021). "HDAC inhibitor studies suggest protection against sepsis-induced vascular leakage by suppressing Hsp90-dependent RhoA activity and signaling." (PMID 31174369, 2019). "Increase in cAMP by adenosine is barrier protective and inhibits RhoA activation in a sepsis model of lung injury." (PMID 31174369, 2019). "If RhoA/ROK activity was disrupted during sepsis, decreasing [Thr855]MYPT phosphorylation, it would be expected that activation of TxA2 receptors would fail to fully restore MLCP inhibition." (PMID 26215803, 2015). "Thus, aberrant RhoA/ROCK signaling cascade stimulation is a mechanism of endothelial barrier dysfunction in sepsis." (PMID 39438952, 2024). "Thus, considering the studies that explored the relationship between vascular reactivity and Rho proteins in sepsis models, the activity of the RhoA/ROCK pathway should be enhanced to increase the vascular tone during the septic insult." (PMID 34440613, 2021). "Both LPS- and adriamycin-induced podocyte cytoskeleton disruption and apoptosis were associated with reduced activity and diminished expression levels of RhoA, reinforcing the putative contribution of Rho proteins for the development of renal dysfunction in sepsis." (PMID 34440613, 2021). "Moreover, drugs with direct effects on Rho proteins, including but not limited to RhoA, Rac1, and Cdc42, remain to be further explored in sepsis." (PMID 34440613, 2021). "Pharmacological activation of Epac1, selective enhancement of Rap1/Rac1 signaling, or targeted suppression of RhoA/ROCK during the repair phase could accelerate endothelial sealing in acute inflammatory conditions such as sepsis, acute respiratory distress syndrome, and ischemia–reperfusion injury." (PMID 41002641, 2025). "The RhoA/ROCK pathway activation seems to be important in lung inflammation, since the pharmacological inhibition of ROCK decreases neutrophil migration and lung edema in experimental models of sepsis." (PMID 34440613, 2021). "The role of RhoA/ROK-mediated inhibition of MLCP extends beyond vascular smooth muscle: thrombin, a key mediator of the cross-talk between coagulation and inflammation in sepsis has, been shown to inactivate MLCP and therefore contraction in a RhoA-dependent manner in human endothelial cells." (PMID 26215803, 2015).
thyroid cancer (11 papers, 2017 to 2025). "The association between miR-154-3p/487-3p and RHOA was further examined by evaluating luciferase activity in human thyroid cancer cell lines K-1 and B-CPAP." (PMID 31820783, 2020). "However, very little is known about the underlying molecular mechanism and the expression of RHOA in thyroid cancer." (PMID 31820783, 2020). "Moreover, the molecular mechanism underlying in miR-154-3p- and miR-487-3p-induced thyroid carcinoma cell growth inhibition and apoptosis was investigated, and the results demonstrated that RHOA/ROCK signaling was implicated in the tumor-suppressive roles of miR-154-3p and miR-487-3p." (PMID 31820783, 2020). "While Rap2 can regulate integrin trafficking in T-cells and thyroid cancer cells, both FAs and acto-myosin stress fibers are also structures regulated by RhoA signaling." (PMID 41200767, 2025). "RhoA activation plays an important role in thyroid cancer cell motility, according to our most recent study." (PMID 34650915, 2021). "The CXCR4/RhoA signaling pathway participates in miR-128-modulated human thyroid carcinoma cells proliferation and apoptosis." (PMID 34322132, 2021). "In thyroid cancer, RHOA/ROCK signaling has a profound stimulative impact to facilitate the invasiveness of anaplastic thyroid cancer cells." (PMID 31820783, 2020). "ADGFR5 (CD97) induces RhoA activation by interacting with the lysophosphatidic acid receptor 1 in thyroid cancer." (PMID 33330053, 2020). "Our present findings expound a novel signal cascade employing miR-154-3p/487-3p and RHOA to fine-tune thyroid cancer cell proliferation and apoptosis." (PMID 31820783, 2020). "In the same research, they also reported that Galectin-3 and Cav-1 were required for RhoA GTPase activation and knocking down of either Galectin-3 or Cav-1 significantly reduced the migration of differentiated thyroid cancer cells." (PMID 29254179, 2017). "Regarding the biological differences in FvPTC in comparison with FA, our analysis found that RhoA signaling, which has previously been reported to be involved in the proliferation and carcinogenesis of thyroid cancer modulated by miR-128, miR-154-3p, and miR-487-3p, was substantially enriched." (PMID 35923625, 2022). "Hence, as the downstream activation of RhoA was observed to be relevant to the migration phenotype, we observed its effects in thyroid cancer cells treated with TSH with a GST-Rhotekin pulldown assay." (PMID 34650915, 2021). "Interestingly, the protein expression of RHOA was significantly negatively correlated with miR-154-3p and miR-487-3p expression in 63 thyroid cancer tissues." (PMID 31820783, 2020). "In addition, the result of correlation analysis showed that the protein expression of RHOA was significantly inversely correlated with miR-154-3p (r = −0.404; P = 0.001) and miR-487-3p (r = −0.456; P < 0.001) expression in thyroid cancer tissues." (PMID 31820783, 2020). "We corroborated that suppression of RHOA by miR-154-3p/487-3p may be a valuable therapeutic target for impeding thyroid cancer progression." (PMID 31820783, 2020). "Furthermore, the protein expression of RHOA was significantly inversely correlated with miR-154-3p (r = −0.404; P = 0.001) and miR-487-3p (r = −0.456; P < 0.001) expression in thyroid cancer tissues." (PMID 31820783, 2020). "In conclusion, our findings highlighted a critical anti-neoplastic role of miR-143 and miR-145 and also showed that RHOA as an oncogene could be post-transcriptionally repressed by miR-143 and miR-145 in thyroid cancer progression." (PMID 31820783, 2020). "The present study was to determine whether miR-154-3p and miR-487-3p synergistically collaborated to regulate RHOA signaling in the carcinogenesis of thyroid cancer." (PMID 31820783, 2020). "Thus, we aimed to investigate the malignant properties of RHOA in thyroid cancer, which might provide a novel therapeutic target in thyroid cancer." (PMID 31820783, 2020).
thyroid cancer (continued). "Therefore, we corroborate that the suppression of RHOA by miR-154-3p/487-3p may be a valuable therapeutic target for impeding thyroid cancer progression." (PMID 31820783, 2020). "IHC staining suggested that a significant increase RHOA protein expression was observed in thyroid cancer compared with adjacent non-tumor tissues, and the protein expression of RHOA was up-regulated in 55 of 63 (87.3%) thyroid cancer tissues." (PMID 31820783, 2020). "In the present study, we found that RHOA protein expression was significantly elevated in 63 thyroid cancer tissues compared with adjacent non-tumor tissues." (PMID 31820783, 2020). "In thyroid cancer, we discovered a collaborative mechanism of miRs that miR-154-3p and miR-487-3p tend to function as tumor suppressors in human thyroid cancer via post-transcriptional repression of RHOA protein expression, but not mRNA levels." (PMID 31820783, 2020).
ischemia (10 papers, 2009 to 2025). A hypoperfusion of the BLOOD through an organ or tissue caused by a PATHOLOGIC CONSTRICTION or obstruction of its BLOOD VESSELS, or an absence of BLOOD CIRCULATION. "Based on our results, we would predict that ROS may activate RhoA signaling in smooth muscle and in the endothelium, contributing to the massive increases in vascular permeability associated with ischemia-reperfusion injury." (PMID 19956681, 2009). "We have previously shown that MMPs and the RhoA/ROCK pathway inhibitor simvastatin have a protective effect on cardiac systolic function in an acute ischemia–reperfusion model by inhibiting the RhoA pathway independently of reducing MMP-2 activity." (PMID 38540212, 2024). "Our recent work further demonstrated that AAV9-mediated expression of L63RhoA in the mouse heart reduces infarct size induced by ischemia, thus activation of RhoA in cardiomyocytes is protective against I/R and MI." (PMID 39122698, 2024). "In the western blot assay, the fimasartan treatment suppressed phospho-ERM and RhoA, which are involved in fibrosis and LV remodeling in the remote myocardium after ischemia." (PMID 30875971, 2019). "Similarly, increases in mitochondrial Parkin levels and ubiquitination of mitochondrial proteins induced by ischemia were also enhanced by RhoA expression." (PMID 35760846, 2022). "Conversely, the addition of LPA attenuated TMP’s inhibitory effect on the RhoA/ROCK pathway, consistent with other studies, and MAP2, a dendritic plasticity-related protein sensitive to ischemia, were both upregulated by TMP treatment." (PMID 40495884, 2025). "Here, using pharmacological and genetic approaches, we provide evidence that activation of RhoA stabilizes PINK1 protein at mitochondria, induces mitophagy, and promotes cardiomyocyte survival against ischemia both in vitro and in vivo." (PMID 35760846, 2022). "This study investigated whether another RhoA/ROCK signaling pathway inhibitor, simvastatin, decreased MMP-2 activity in a rat model of ischemia-reperfusion injury by inhibiting the RhoA/ROCK pathway and reducing MMP-2 mRNA levels." (PMID 36139129, 2022). "Subjecting the ischemia-affected CMC to secretome, time-dependent increase of HIF-1α and RhoA expression could be detected, indicating that cell-free therapy might be considered as a more viable option for cardiac regeneration." (PMID 33123511, 2020). "While mounting evidence suggests that the RhoA-ROCK signaling pathway is a promising therapeutic target for CNS injuries including spinal cord injury and ischemia, it is not known whether inhibiting RhoA signaling will enhance neural protection and repair and restore cognitive function after TBI." (PMID 28878396, 2017).